CD44 (CD44 molecule (IN blood group))
Diseases named in the same sentence as CD44 in open-access papers (continued):
Sharing a sentence is not in itself a finding about the gene and the disease.
colorectal cancer (continued). "The expression of CD44 in various solid tumors, such as colorectal cancer, lung cancer, and Ewing’s sarcoma, differs from that in normal tissues, indicating its important role in tumorigenesis." (PMID 40240758, 2025). "In contrast, the use of HA as a targeting ligand in the albumin nanoparticles, PP-HA-BSA-NPs, significantly improved drug delivery in CD44-expressing triple-negative breast cancer and colorectal cancer cells." (PMID 41002533, 2025). "In colorectal cancer, CAFs increased the stemness and the migration ability of cancer cells in liver or lung metastasis by upregulating CD44 expression through HGF/MET/AKT signal pathway." (PMID 41346572, 2025). "It was identified that CD44 isoforms 2, 3 and 4 are predominantly expressed in colorectal cancer patients at the mRNA expression levels." (PMID 40114966, 2025). "Previous studies have shown that CD44 overexpression promotes cancer cell migration and invasion in breast, ovarian, and colorectal cancers." (PMID 39833941, 2025). "In this study, we discovered that decreased CLCA4 expression was evident in CD133+CD44+ colorectal CSCs and chemoresistant colorectal cancer (CRC) cells." (PMID 41674659, 2025). "CD44 and Lgr5 were surface markers of colorectal cancer stem cells, which played important roles in colorectal cancer metastasis and progression." (PMID 40611658, 2025). "A systematic review and meta-analysis on the role of CD44 in colorectal cancer suggested that IHC is a more reliable method than ELISA, since serum CD44 levels are affected not only by cancer but also by immune system activity." (PMID 41440277, 2025). "CD49f acts as a functional marker for maintaining the stemness of colorectal cancer cells, and CD49f+/CD44+ cells display strong capabilities of self‐renewal and multidifferentiation." (PMID 41346572, 2025). "These liposomes can be designed to target CD44-overexpressing cancer cells, which are prevalent in lung and colorectal cancers." (PMID 39055490, 2024). "A recent study indicates that CD44/CD133-positive colorectal cancer stem cells are sensitive to trifluridine (FTD) exposure." (PMID 38953895, 2024). "CD44 is a crucial factor in colorectal cancer, with specific isoforms demonstrating their significance in the development, progression, metastasis, and resistance to therapy." (PMID 38672650, 2024). "For example, in colorectal cancer, CD44-expressing cells exhibit high tumorigenic capacity and are capable of initiating tumor formation in xenograft models." (PMID 39518076, 2024). "CD44 expression appears to be a marker of poor prognosis and clinical recurrence in many types of cancer, such as kidney, thyroid and colorectal cancer." (PMID 39020106, 2024). "A human antibody fragment, AbD15179, which is well characterized for its specificity for human CD44v6, an alternatively spliced CD44 isoform known to be overexpressed in 50% of colorectal cancers, was exploited for drug delivery in colon tumors." (PMID 38543324, 2024). "For instance, in colorectal cancer, silencing ZMAT3 can promote the proliferation of cancer cells by increasing the inclusion of CD44 variant exons." (PMID 39664194, 2024). "In this review, we aim to highlight the predictive and prognostic significance of CD44 in various cancer types, with a particular focus on colorectal cancer." (PMID 38672650, 2024). "The expression of CD44 was shown to be aberrantly up‐regulated among several tumors, including colorectal cancer (CRC)." (PMID 37849446, 2024). "Specifically, CD44 appears to play a crucial role in colorectal cancer (CRC), where specific isoforms have been shown to play a central role in carcinogenesis, progression, metastasis, and resistance to therapy." (PMID 38672650, 2024). "It has been also demonstrated that TAMs interact with CD44 in CSCs through OPN to regulate CSC-mediated tumor progression by activating the PI3K/Akt in colorectal carcinoma." (PMID 39062100, 2024).
colorectal cancer (continued). "The reciprocal crosstalk between TAMs and cancer cells via OPN/CD44 axis advances the tumorigenicity through activation of the JNK pathway in colorectal carcinoma." (PMID 39062100, 2024). "In colorectal cancer, radiotherapy activates the PI3K/AKT signaling pathway, which in turn causes upregulation of SOX2 expression, ultimately leading to increased CD44+ cells and enhanced radioresistance." (PMID 37213675, 2023). "It reduced the CD133+CD44+ subpopulation in HCT116 colorectal cancer cells, which was correlated with the upregulation of PTEN and downregulation of FASN expression." (PMID 37298797, 2023). "Our goal was to investigate how different CD44 isoforms contribute to the emergence of stem cell (SC) overpopulation that drives colorectal cancer (CRC) development." (PMID 37005380, 2023). "RNAi-mediated silencing of NANOG expression suppressed proliferation and increased apoptosis in the EpCAM+/CD44+ CSC population of HCT116 colorectal cancer cells." (PMID 37047234, 2023). "For example, its intrinsic expression in colorectal cancer cell lines decreased E-cadherin expression and increased stem cell-associated markers such as N-cadherin, vimentin, CD133, CD44, and OCT4." (PMID 36901916, 2023). "Research comparing colorectal cancer (CRC) xenograft derived from different percentage of EpCAM/CD44 cells discovered that EpCAMhigh/CD44+ cell group possesses the highest level of tumorigenicity." (PMID 38455361, 2023). "SUMO inhibitors inhibit colorectal cancer growth, invasion, and metastasis by inhibiting the CSCs population through the inhibition of CD44 and MMP14." (PMID 37777749, 2023). "A meta-analysis study involving 3098 colorectal cancer patients demonstrated that CD44v6 serves as a superior prognostic biomarker for survival rate compared to CD44." (PMID 37491225, 2023). "Colorectal cancer stem cells (CCSCs) identified by specific surface markers, such as CD44 and CD133, have been extensively studied." (PMID 36750842, 2023). "In this study, AKT inhibitor (MK-2206 2HCl) or FAK inhibitor (PF-562271) decreased the expression of stem cell markers (Nanog, OCT4, CD133, CD44, c-Myc) and spheroid formation in colorectal cancer." (PMID 37083591, 2023). "The CSCs of colorectal cancer are CD44+/hiALDH+/hi cell population which are mediated by SUMO-unconjugated TFAP2A." (PMID 37777749, 2023). "Studies have documented the crucial role of CD44 in tumor formation, chemotherapy resistance, and progression of metastatic disease in colorectal cancer, establishing it as a key surface marker in colorectal cancer stem cells." (PMID 38069256, 2023). "CD44 is also a major Wnt target gene in the intestine, and it is essential for Wnt-induced tumor progression in colorectal cancer." (PMID 37958796, 2023). "The CD44 protein was overexpressed on the colorectal cancer cells compared with the normal colon epithelial cells (NCM460)." (PMID 37161591, 2023). "Related to this, the alternative splicing of CD44 was reported to enhance the colonization of metastatic lung and colorectal cancer cells." (PMID 38069324, 2023). "The surface markers of the tumor-initiating cell subsets of Caco-2 colorectal cancer cells are mainly CD44 CD133." (PMID 35836256, 2022). "In this study, we found that upregulation of miR-6511b-5p by miRNA mimics diminished the expression of CD44 and reduced the migratory and invasive ability of colorectal cancer cells." (PMID 35590122, 2022).
colorectal cancer (continued). "The results showed that LINC01315 was high-expressed in CD133+/CD44+ colorectal cancer stem cells and exosomes." (PMID 35470736, 2022). "In vitro, overexpression of miR-6511b-5p inhibited metastasis by decreasing CD44 expression via directly targeting BRG1 in colorectal cancer." (PMID 35590122, 2022). "The results revealed that miR-6511b-5p expression was low, while BRG1 and CD44 expression was high in pMMR colorectal cancer tissues." (PMID 35590122, 2022). "Colorectal-cancer-CAFs-derived HGF induced up-regulation of CD44 which mediated adhesion of CRC cells to endothelial cells, and subsequently resulted in enhancement of metastasis of CRC." (PMID 35936516, 2022). "Overall, our findings demonstrated that miR-6511b-5p inhibited metastasis in MSS colorectal cancer cells via the negative regulation of CD44." (PMID 35590122, 2022). "Previous studies have indicated the necessity of BRG1 for the transcription and expression of CD44 in colorectal cancer." (PMID 35590122, 2022). "Mechanism studies have shown that TRIM29 can activate the Wnt/β-catenin signaling pathway by up-regulating the expression of CD44 in colorectal cancer." (PMID 35836256, 2022). "Mechanistically, miR-6511b-5p suppresses invasion and migration of colorectal cancer cells through methylation of CD44 via directly targeting BRG1." (PMID 35590122, 2022). "As a result, CD133+/CD44+ colorectal cancer stem cell-derived exosomal LINC01315 was found to promote the proliferation, migration, and stemness of colorectal cancer cells." (PMID 35470736, 2022). "CSCs are characterized by expression of surface markers that includes CD133, CD44 and EpCAM which are of specific relevance to colorectal cancer." (PMID 35642021, 2022). "All these discoveries demonstrated that CD133+/CD44+ colorectal cancer cell-derived exosomes containing a high level of LINC01315 the stemness of colorectal cancer cells." (PMID 35470736, 2022). "Consistent with our study, hypermethylation of CD44 promoter also promoted downregulation of CD44v6 expression in liver cancer and colorectal cancer." (PMID 36163632, 2022). "Taken together, these results demonstrate that miR-6511b-5p inhibits the expression of CD44 by directly targeting BRG1 in colorectal cancer." (PMID 35590122, 2022). "We then measured the sensitivity of HCT116‐CSCs to oxaliplatin following CD44 silencing, a third‐generation platinum drug as first‐line chemotherapy for colorectal cancer." (PMID 35229451, 2022). "And the combination of positive CD44 and CD133 showed the same overall survival result as positive CD44 alone, in which CD44 is effective in assessing the prognosis of colorectal cancer." (PMID 36415383, 2022). "All these phenomena verified that LINC01315 silencing inhibited the stemness of CD133+/CD44+ colorectal cancer cells." (PMID 35470736, 2022). "We haveevaluated the specificity of this formulation for CD44-expressingcancers and have demonstrated effective CD44-dependent cytotoxicityin both breast and colorectal cancer cells." (PMID 35938983, 2022). "CD44 is linked to a significant potential biomarker for diagnosing colon cancer stem cells, which arise an alert for developing a therapy that targets CD44 to reduce mortality among colorectal cancer patients." (PMID 36415383, 2022). "Collectively, our observations and findings indicate that the metastasis-repressive role of miR-6511b-5p in colorectal cancer is mediated by a CD44-dependent pathway." (PMID 35590122, 2022). "In colorectal cancer, the heparin-like and chondroitin sulfate B side chains of CD44 bind to the laminin A5G27 peptide." (PMID 35936713, 2022). "A previous study showed that enhancement of CD44 resulted in EMT changes, including mesenchymal markers and epithelial markers, indicating the possibility that CD44 is involved in EMT in colorectal cancer cells." (PMID 35590122, 2022).
colorectal cancer (continued). "In general, we found that miR-6511b-5p suppresses colorectal cancer cells invasion and migration through impairing CD44 expression via directly targeting BRG1." (PMID 35590122, 2022). "Real-time PCR and immunohistochemistry were conducted to assess the expression of BRG1 and CD44 in 40 fresh pMMR colorectal cancer tissues and consecutive tissue microarrays, respectively." (PMID 35590122, 2022). "Second, we conducted invasion assays and wound healing assays to investigate the role of miR-6511b-5p and CD44 in colorectal cancer cells metastases." (PMID 35590122, 2022). "The expression of CD44 mRNA was positively correlated with BRG1 in colorectal cancer tissues (Pearson correlation: 0.563, P < 0.001, R2 = 0.3164)." (PMID 35590122, 2022). "Both CD133 and CD44 proteins are the key markers for a subset of human colorectal cancer stem cells." (PMID 35470736, 2022). "TGF-β, produced by activated lymphocytes, induces NF-kappaB activation and EMT, and enhances stemness by CD44 expression in colorectal cancer." (PMID 34884696, 2021). "We found that CCNP increases spheroid formation in breast, lung and colorectal cancers, and upregulates the expression of stemness (CD44, CD133) and pluripotency (SOX2, OCT4, NANOG) markers." (PMID 34604945, 2021). "This correlated expression of Reg4, CD44 and CD44ICD establishes an important axis of Reg4-CD44-CD44ICD, a hallmark suggesting a crucial role in colorectal cancer biology." (PMID 33659040, 2021). "Relevant for colorectal cancer, CD44 not only acts as a positive regulator of the Wnt pathway at the level of the signalosome, but is also a Wnt target gene (." (PMID 33671641, 2021). "The colorectal cancer cell lines that were studied expressed CD44 (CD44-positive, CD44+) and CD133 (CD133-positive, CD133+) at various frequencies." (PMID 33994850, 2021). "The population of HCT116 and HT29 cells each contained approximately 70% CD44+CD133+ cells, indicating that the frequencies of CD44+CD133+ subpopulations vary among colorectal cancer cell lines." (PMID 33994850, 2021). "We previously demonstrated that a splice variant of CD44, CD44 variable alternative exon 6 (CD44v6), is highly and specifically expressed by CTC cell lines derived from blood samples in colorectal cancer (CRC) patients." (PMID 34638450, 2021). "In that study, purported CSCs were isolated from the HT29 colorectal cancer cell line through CD44-positive selection using magnetic beads." (PMID 34201298, 2021). "CD133+/CD44+ cancer cells, which have the properties of tumour progenitor cells, are critical in the tumorigenesis of colorectal cancer." (PMID 33790909, 2021). "TAMs and EpCAM+CD44+ colorectal cancer cells were isolated from human tumor-derived colorectal cancer xenografts, and then cancer cells were inoculated into nude mice with or without TAMs." (PMID 34209679, 2021). "A study indicated that Musashi-1 has a fundamental role in increasing the extension of CD44+ colorectal cancer stem cells and SG formation." (PMID 35004322, 2021). "The properties of CSCs, including spheroid-like growth and metastatic potential, were observed in SOX2-positive colorectal cancer with an increased expression of CSC markers such as CD44." (PMID 33445526, 2021). "Even though we did not observe consistently lower or higher levels of HAS, HYAL2 or CD44 correlativity tests for colorectal cancer show a strong positive correlation between HAS, HYAL and CD44; many of them with strong statistical significance." (PMID 32610620, 2020).
colorectal cancer (continued). "In other study, the supplementation of pomegranate extract in patients with colorectal cancer had a significant down-regulating effect on the expression of colorectal cancer-related genes such as CD44, CTNNB1, CDKN1A, and EGFR in surgical colon samples." (PMID 33322700, 2020). "For example, in colorectal cancers, expression of CD44/CD166 characterizes a cell population able to form tumor spheres, suggesting anchorage-independent proliferation of these cells." (PMID 32849491, 2020). "Evidence exists for the presence of cancer stem cells in colorectal cancer, with some phenotypes being CD44+/CD166+ enriched CSCs." (PMID 32430068, 2020). "The addition of HA increased the binding of the HDAPPs in vitro, ex vivo and in vivo to CT26 murine colorectal cancer cells that expressed CD44." (PMID 32328438, 2020). "GLI1 inhibition was shown to revert chemo-resistance in organoids from colorectal cancer patients, and concurrently down-regulated cancer stem cells markers, such as c-Myc, CD44 and Nanog9." (PMID 32814794, 2020). "Our results show inconsistencies in CD44 expression in both, breast and colorectal carcinoma patients." (PMID 32610620, 2020). "Hyaluronic acid-coated chitosan NPs loaded with 5-fluorouracil (5-FU)/oxaliplatin enhanced cytotoxicity compared with either 5-FU or oxaliplatin alone in human colorectal cancer cells, which overexpressed CD44." (PMID 31013960, 2019). "In brief, our results showed that CC-CAFs promoted metastasis of colorectal cancer by up-regulation of CD44 through HGF/MET/AKT signal." (PMID 31367190, 2019). "Metformin treatment selectively reduced the CD44+/CD133+ fractions in four out of eight colorectal cancer cell lines and prevented sphere formation in said population." (PMID 31661927, 2019). "CD44, a transmembrane protein may involve in the process, has been reported to be adhesion molecular and mediator of adhesion between tumor cells and endothelial cells which could promotes subsequently metastasis, and has also been shown to be associated with bad prognosis in colorectal cancer." (PMID 31367190, 2019). "CC-CAFs-CM resulted in increased phosphorylation of MET, AKT and expression of CD44 in colorectal cancer cells." (PMID 31367190, 2019). "Stem cell surface markers like CD133, CD44, or EpCam have been used to enrich colorectal cancer TICs and to reflect their tumor-initiating properties." (PMID 30763370, 2019). "KCTD12 over expression in colorectal cancer repressed stemness through down regulation of CD44, CD133, and CD29." (PMID 30157793, 2018). "Colorectal cancer stem cells express several cell surface markers, such as CD44, CD24, CD133 and CD146." (PMID 29642386, 2018). "In the mouse intestinal polyps, DCLK1+ cells in part co-express other stem-cell-associated markers, such as CD44, LGR5 and CD133; furthermore, DCLK1+ cells have been observed in human colorectal cancers." (PMID 29652830, 2018). "CD44-positive colorectal cancer cells co-cultured with macrophages produced higher levels of OPN that facilitated tumorigenicity and clonogenicity." (PMID 29747682, 2018). "Actually, a positive correlation between the CD44 decrease and the therapeutic response of patients with colorectal cancer has been recently identified." (PMID 29348560, 2018). "CD44 is not only a common biomarker of CSCs in cancers, such as colorectal cancer, lung cancer, and glioblastoma, but also a receptor of hyaluronan." (PMID 30021598, 2018). "Next, we investigated the expression of surface and intercellular molecules linked to cancer stem cell (CSC) markers in human colorectal cancer cells, including CD133, CD44 and ALDH1, which are most widely used to characterize CSC." (PMID 30002278, 2018).